IFNG (interferon gamma)
Diseases named in the same sentence as IFNG in open-access papers (continued):
Sharing a sentence is not in itself a finding about the gene and the disease.
infection (continued). "This suggests that Mrgpra1 regulates IFNγ-dependent neutrophil function during infection." (PMID 38295799, 2024). "Importantly, CAF01 subunit vaccination also elicited robust Th1 and Th17 immune responses following infection, and IFNγ responses correlated with fungal control as measured by lung CFUs." (PMID 38712080, 2024). "In the early acute phase (3–5 weeks post-infection), type 1 helper T cells (Th1) mediate the immune response by secreting cytokines such as interferon gamma (IFNγ), interleukin 1 (IL-1), and tumor necrosis factor-alpha (TNFα), targeting the migrating schistosomula." (PMID 39264964, 2024). "Indeed, ILC1s in the liver mediate IFNγ-dependent antiviral effects against MCMV in the earliest stages of infection." (PMID 38684766, 2024). "We found that mice defective in IFNγ responsiveness (IFNγR−/− mice) were not protected after HK-fbp1 vaccination and were as susceptible to infection as unvaccinated mice." (PMID 39324785, 2024). "An approximately tenfold increase in IFNα and IFNγ levels was detected after LEV-8 infection." (PMID 38932201, 2024). "As we had seen before, post-infection, neutrophils gained IFNγ and lost NPFF in vivo." (PMID 38295799, 2024). "Notably, the hepatic expression of type I and type II cytokines like Tnfα, Ifnγ, Il12, or Il4, as well as regulatory cytokines like Il10, showed maximum expression at the youngest age of infection similar to egg load and granuloma extent." (PMID 39404406, 2024). "This is evidenced by the increased amounts of IFNγ produced by the expanded memory CD8 + T cells following VV-WR infection as well as the increased protection seen with a lower bacterial burden during a pathogenic re-challenge with the archived antigen from the immunization." (PMID 38514656, 2024). "Our data indicated that fat loss significantly increases TNFα levels and does not alter IFNγ levels in both males and females compared to RD-fed mice during infection." (PMID 38999932, 2024). "Notably, IFNγ is required for the clearance of primary C. burnetii infection, but appears to be less critical for clearance during secondary infection in mice." (PMID 37885896, 2023). "Thus, the effect of perforin was rather limited, while the infection in IFNγ -/- and CD8+ T-cell depleted mice continued to develop, indicating substantially reduced immunity from the combined vaccination in these mice." (PMID 38164135, 2023). "To investigate how IFNγ directly mediates the fetal hematopoietic response within the complex framework of infection, we also compared the effects of maternal T. gondii infection with varying degrees of virulence to a single maternal cytokine injection of IFNγ." (PMID 37259639, 2023). "The differences in the response of HSCs and progenitors to IFNγ alone compared to IFNγ in the context of a complex infection led us to investigate the degree to which maternal or fetal IFNγ was responsible for the hematopoietic changes induced by T. gondii infection." (PMID 37259639, 2023). "and Plasmodium spp., trigger a cell-mediated T helper 1 (Th1)-type immune response, which involves the activation and recruitment of phagocytic cells (macrophages and neutrophils) and secretion of inflammatory cytokines, such as interferon gamma (IFNγ) and interleukin 2, to the site of infection." (PMID 37111135, 2023). "The results suggest that IFNγ-producing B cells may play a critical role in the modulating effect of infections on allergic responses." (PMID 37759658, 2023). "H5N1 whole-inactivated virus (WIV) immunization via intranasal and intramuscular route induced a comparable frequency of multifunctional Th1 CD4+ cells, whereas PR8 WIV strain infection induced a higher IFNγ-secreting CD4+ T cells in spleen only in intranasal route." (PMID 36626205, 2023). "Interferon gamma is produced in the host defense against infection and may be elevated during autoimmune and inflammatory diseases." (PMID 37298597, 2023).
infection (continued). "As expected, large numbers of CD4 and CD8 T cells produced Ifnγ at day 10 post infection." (PMID 37842651, 2023). "Of note, enhanced NK cell degranulation and IFNγ accumulation upon infection with MV encoding non-relevant HMWMAA-scFv-Fc compared to unmodified MV did not correlate with increased HT-29 target cell death." (PMID 36765035, 2023). "Because only a subset of CD8+ T cells expressed IFNγ in the skin on day 7 after infection, we next tested whether all of the effector CD8+ T cells isolated from the skin had the potential to express IFNγ in response to TCR stimulation." (PMID 37402742, 2023). "Interestingly, the reduction of IL-10 secreting cells by IFNγ translated to bulk cultures, suggesting that during infection homeostasis is more easily steered into excessive inflammation, rather than insufficient response." (PMID 36911668, 2023). "The IFN system was mostly involved in response to both types of infection in mouse lungs and in U937 cells, while in A549, the transcription of IFNs remained unchanged or slightly increased (the expression of IFNG was even decreased at 4 h p.i. with C. pneumoniae)." (PMID 37686095, 2023). "In addition to GRA57 and its 2 partner proteins, we show that 2 components of the MYR effector export machinery, MYR1 and MYR3, are important for parasite survival in IFNγ-activated HFFs in both pooled and single knockout infections." (PMID 37459303, 2023). "The response may be a result of the increased Ifnγ + NK cells in the lymph node after the initial infection." (PMID 37842651, 2023). "The apparent drop in CD8+ IFNγ and TNF responses to Delta peptides compared with ancestral peptides among cases was particularly striking and suggests a role for cross-reactive CD8+ T cells in protection against infection with the Delta variant." (PMID 37655880, 2023). "The finding suggests that IFNγ-producing B cells play a significant role in the infection-mediated inhibition of allergic reactions and imply that this type of B cell may be involved in a broader spectrum of immune regulation." (PMID 37759658, 2023). "However, this was not the case for TNF, the transcription of which was enhanced by the infection independently of IFNγ." (PMID 37383236, 2023). "We found the highest median IFNγ-production 1 month after infection (15,806 pg/mL), which significantly decreased at the subsequent study visits (5,144 pg/mL (p = 0.0004); 1,885 pg/mL (p < 0.0001) and 5,214 pg/mL (p < 0.0001) at month 10, 13 and 20, respectively)." (PMID 37974069, 2023). "Compared to the parental RH strain, CD8 T cell IFNγ responses were slightly elevated to BMDMs infected with RH Δgra35 and RH Δgra42 strains, but significant differences were only observed in response to RH Δgra43 infections." (PMID 37287466, 2023). "For example, the test could be used to confirm a diagnosis of bTB in suspect cases, detect bTB infected animals missed by SICCT or IFNγ tests, or to aid resolving infection status of animals showing an inconclusive reaction in a TT test." (PMID 36726018, 2023). "A major inducer of IFNγ is IL-12, which is present at the site of infection." (PMID 37298597, 2023). "In the initial stage of infection, T. gondii is recognized by innate immune response cells, stimulating dendritic cells, macrophages and neutrophils to produce interleukin-12 (IL-12) and inducing natural killer (NK) cells to produce interferon-gamma (IFN-γ)." (PMID 37624234, 2023). "Furthermore, the temporal increase in the donor CD4+IFNγ+ Tregs indicates replication of these donor Tregs in the recipient mice over the course of the infection as previously reported." (PMID 37965256, 2023). "In addition, combination therapy with target-specific vBiKE starting after the 36 h coculture period elicited elevated cytokine expression and IFNγ accumulation was marginally increased upon MV-NIS compared to mock infection." (PMID 36765035, 2023). "We examined Ifnγ expression at four different time points following infection." (PMID 37842651, 2023).
infection (continued). "Indeed, infected Acod1−/− mice expressed higher mRNA levels of Il6, IFNγ, Nos2 and Gbp1 than wild‐type controls in the lungs, but also in the spleen, after intratracheal infection." (PMID 36479617, 2023). "Furthermore, the majority of IFNγ-producing IL-18R+ ILCs were able to proliferate after infection and displayed an immature phenotype." (PMID 36838426, 2023). "Subsequent to infection, M. tb is phagocytosed by antigen-presenting cells (APCs) that participate in the extermination of internalized pathogens, promote activation of T lymphocytes and stimulate protective pro-inflammatory cytokines such as IFNγ and IL17." (PMID 36881595, 2023). "It remains unclear if upon infection with Toxoplasma, the cholesterol levels within the host cells are affected in IFNγ-stimulated HFFs." (PMID 36916910, 2023). "Moreover, over the course of infection, IL-18R+ ILCs start to express T-bet with the concomitant IFNγ production to acquire a ILC1-like phenotype." (PMID 36838426, 2023). "Similarly, lung CD4 and CD8 T cells increased their expression of Ifnγ at day 10 post-infection, matching their increase in cell number." (PMID 37842651, 2023). "Further, lung CD4+ T cells had significantly increased Th1 (IFNγ) and Th2 (IL-4, IL-5, IL-13) cytokine production potential during patent schistosome infection, at a greater magnitude than observed in pre-patent infection." (PMID 37012228, 2023). "Although IFNγ produced by ILC1s is important for protection against the parasite at the onset of the infection, NK cells and T cells are critical for protection at the later stages of infection." (PMID 36838426, 2023). "TH1- and TH2-related transcripts included Nfatc1, Cd4, Runx3, and Gata3, suggesting that TH1 cells may be a significant contributor to interferon-gamma (IFNγ) production during infection in the adipose tissue." (PMID 37923768, 2023). "Consistent with reduced IFNγ expression, the mRNA induction of Nos2, Gbp1, Gbp2, Gbp4, Gbp5, Ido1 and Acod1 was severely impaired in the spleens of Myd88−/− mice after intraperitoneal infection." (PMID 36479617, 2023). "In addition to immune modulating function, which mediates broad immune defense against infection, IFNG can play a role in direct antiviral effects on infected cells and neighboring cells." (PMID 37052473, 2023). "IFNγ is a pivotal cytokine that promotes innate and adaptive immunity during infection." (PMID 37797010, 2023). "To test the sensitivity of the OT-I TCR to these altered peptide ligands (APLs), we isolated effector OT-I CD8+ T cells from the spleen on day 7 post VacV-SIINFEKL infection and quantified the concentration of peptide required for a half-maximal IFNγ-YFP response (EC50)." (PMID 37402742, 2023). "While NMII strongly replicated in Acod1−/− BMM, treatment with IFNγ starting 4 h after the infection, when extracellular NMII were washed away, inhibited bacterial replication in both WT and Acod1−/− BMM as shown by qPCR for C. burnetii GE and immunofluorescence staining (Fig EV1)." (PMID 36479617, 2023). "IFNγ promotes macrophage activation by inducing pro-inflammatory cytokine and chemokine production, upregulating antigen presentation and ROS production, sustaining antileishmanial responses and infection control." (PMID 37764937, 2023). "Because D21SPN NK cells showed higher expression of IFNγ upon secondary stimulation in vitro, we hypothesized that IFNγ production by memory NK cells in vivo could be an important factor for protecting mice against lethal infection." (PMID 37486946, 2023). "How Toxoplasma survives after infection of human cells that were previously stimulated with IFNγ is largely unknown." (PMID 36916910, 2023). "This may also act as a counterbalance to pro-inflammatory IFNγ and TNFα that were also upregulated by vaccination, both of which play a role in the clearance of infection but also in pathology development." (PMID 36799886, 2023).
infection (continued). "In the present study, almost three years after the beginning of the pandemic, we had the possibility to look at SARS-CoV-2-specific T cell responses over 540 DPSO and demonstrated well detectable IFNγ+ responses (in 65% of donors) one-year post-infection, with sharp decline at 18 months PSO." (PMID 37046496, 2023). "Additionally, by comparing the numbers of Ifnγ+ cells from the different populations in the Med LN and lung at days 10 and 40 post-infection, we found that CD4 and CD8 T cells were the largest population of cytokine+ cells." (PMID 37842651, 2023). "Additionally, infection with Legionella has sporadically been described in patients with the presence of anti-IFNγ auto-antibodies." (PMID 38203686, 2023). "Similarly, IFNγ treatment of unpolarised macrophages after establishment of infection led to higher S.tm CFU in BMDM as compared to IL-4 stimulation." (PMID 37190073, 2023). "For instance, genetic variants in IL13, IL4, IL10, IFNG and STAT6 genes were associated not only with infection intensities and re-infection of S. mansoni after treatment, but also with S. haematobium infections and its infection intensities." (PMID 36889485, 2023). "IFNγ has long been shown to be the major player in the control of Tg with studies in mice revealing a dose-dependent effect of monoclonal antibodies to IFNγ on survival after Tg infection." (PMID 37975677, 2023). "After infection with T. gondii, DCs, macrophages and neutrophils are activated and secrete proinflammatory cytokines, including IL-12, which stimulates NK cells, ILCs and T cells to secrete IFNγ." (PMID 36430676, 2022). "Protection against Mtb requires a distinctly defined type 1 response, mediated by interferon-gamma (IFNγ), IL-2, and tumor necrosis factor-alpha (TNFα), which may clear the infection or restrain it into an immune-mediated containment, also known as latency." (PMID 36006249, 2022). "Taken together with the fact that Ifnγ−/− mice develop increased mucosal damage 14 days after infection with C. rodentium, it is reasonable to consider that cIECs could play a similar role during and after C. rodentium infection." (PMID 35100877, 2022). "Almost no CD4T cells produced IFNγ spontaneously in unvaccinated mice prior to PbA challenge (naive mice: 0.42%, 51 × 103 cells, mean value), but a substantial portion of CD4T cells produced IFNγ in response to PbA infection (control PbA: 1.9%, 162 103 cells, mean value)." (PMID 35632518, 2022). "In addition, the correlation of CSP-specific, IFNγ-producing CD4 T cells with protection from infection following RTS,S/AS02 vaccination also suggests that Th1 cells can contribute protective immunity in humans." (PMID 35108339, 2022). "Despite being situated along with similar positions, such significant similarities and minor differences between amino acid orders can be attributed to similarities in both serotypes, such as their effect on the host’s interferon-gamma production (IFN-γ) during infection." (PMID 36016147, 2022). "Also, IFNγ is regarded as critical in the Th1-dependent immune responses and leads to the restriction of bacterial multiplication in the early stage of the infection." (PMID 36409703, 2022). "Notably, in naturally exposed participants from the Dutch village cohort assessed more than a decade past infection, adaptive cytokine responses were as high (IL-2) or higher (IFNγ and IP-10) than those observed 4-5 weeks after vaccination." (PMID 35812430, 2022). "The extended presence of ZIKV may also explain the continued increase in the expression of inflammatory genes and pro-inflammatory cytokines such as interferon-gamma (IFN-γ) in the CNS more than one year post-infection." (PMID 35897696, 2022). "All mice neutralized of IFNγ fatally succumbed to WT infection within 20 days, while a ~35% survival rate was observed for mice with abrogated IL-17A signaling either through direct cytokine neutralization or IL-17-directed effector cell depletion (i.e., neutrophils)." (PMID 36229573, 2022).
infection (continued). "In accordance with these reports and our finding of higher IFNγ levels in highly susceptible BALB/c mice, we tested if blocking IFNγ and TNF might reduce disease severity after maVie16 infection." (PMID 35023830, 2022). "Due to the important role of ZNF683 in the immune system, we speculate that high expression of ZNF683 promotes CD8+ T cell IFNγ secretion and proliferation after infection to inhibit viral replication and slow the disease progression." (PMID 35458449, 2022). "Overall, in animal models of T. cruzi experimental infection, either T helper (Th)-1 or Th1/Th2 balanced and Th-17 immune responses are required to achieve parasite control with evidence for the importance of IFNγ and CD8+ T cells." (PMID 36095001, 2022). "It has recently been shown that activated IFNγ signaling, in the experimental context of infection or exogenous administration, is a strong driver of the clonal expansion of cells carrying loss-of-function mutations in the gene DNMT3A, by far the most prevalent mutation found in CH." (PMID 36496394, 2022). "IFNγ, IP-10 and IL-2 responses were strongly elevated in individuals with prior C. burnetii antigen exposure, whether through infection or vaccination, while IL-1β, IL-6 and TNFα responses were slightly increased in naturally exposed individuals only." (PMID 35812430, 2022). "In collaboration with AMC Amsterdam, a cohort of seven D+R− kidney transplant patient samples from multiple timepoints post transplantation were analyzed using IFNγ and IL-10 FluoroSpots to establish when post-infection HCMV-specific T cells to a broad range of proteins develop." (PMID 36558866, 2022). "A compelling study in healthcare workers has shown higher frequencies of IFNγ-producing ORF-1 reactive T cells to be associated with a lack of infection as determined by the absence of seroconversion during the first wave of the pandemic in the UK29." (PMID 35013199, 2022). "Higher expression of ZNF683 promotes CD8+ T cell IFNγ secretion and proliferation after infection." (PMID 35458449, 2022). "IL-18 is indeed an inducer of IFNγ production, and it activates T cells and NK cells in synergy with IL-12; thus, its release in response to infection with attenuated strains might promote T cell responses." (PMID 35215216, 2022). "The interferon-gamma-related function may have been activated in chickens immediately after infection (i.e., before the first sampling), and the downregulation began prior to 4 dpi." (PMID 36003329, 2022). "We also examined the relationship between infection of ABCs and expression of IFNγ." (PMID 36477199, 2022). "In addition, the infection induced an increase in interferon gamma (IFNγ) and tumor necrosis factor-alpha (TNF-α) in the intestine in the acute phase, in which this increase continued until the early chronic phase." (PMID 35069009, 2022). "In addition, TgPrx1KO and TgPrx3KO induced high levels of interferon gamma (IFN-γ) in infected mice at 8 days post infection, and increased IL-6 and IL-12p40 production from murine macrophages cultivated in vitro." (PMID 35328497, 2022). "Using experimental mouse models of infection, studies identified the production of the pro-inflammatory cytokine IFNγ by NK, NKT and TH1 cells, together with the release of several parasite-derived components, as major driving force in the activation of myeloid cells." (PMID 35464430, 2022). "Under inflammatory conditions, in infections or cancer, IFNγ induces an increased expression of MHC I and proteins involved in antigen processing and presentation (APP), including tapasin, resulting in an increase in antigen processing, transport, and presentation." (PMID 36389776, 2022). "In the case of IFNγ in males, infection by T. crassiceps induced a decrease in this cytokine." (PMID 35335632, 2022). "To further determine whether T cell recruitment resulted in changes to the lung cytokine milieu, we examined IFNγ and IL-17 levels in lung lysates obtained at weeks 2, 3, and 4 post infection." (PMID 35173157, 2022).